PYGM (glycogen phosphorylase, muscle associated)
Diseases named in the same sentence as PYGM in open-access papers (continued):
Sharing a sentence is not in itself a finding about the gene and the disease.
head and neck squamous cell carcinoma (3 papers, 2019 to 2024). A squamous cell carcinoma that arises from any of the following anatomic sites: lip and oral cavity, nasal cavity, paranasal sinuses, pharynx, larynx, and salivary glands. "PYGM can also be a biomarker for head and neck squamous cell carcinoma." (PMID 38483604, 2024). "PYGM is significantly downregulated in head and neck squamous cell carcinoma (HNSCC) and correlates with worse prognosis of HNSCC." (PMID 33708772, 2021).
schizophrenia (3 papers, 2016 to 2022). A major psychotic disorder characterized by abnormalities in the perception or expression of reality. "The research has found that in the astrocytes of schizophrenia, the levels of PYGM and RAC1 (a kinase that regulates the activity of PYGM) involved in astrocytes metabolism are reduced, leading to a transient partial energy deficiency in the dorsolateral prefrontal cortex." (PMID 35990602, 2022). "The metabolic pathway in astrocytes, involving PYGM, could contribute to a transient local energy deficit in DLPFC in schizophrenia." (PMID 33924466, 2021).
colorectal cancer (2 papers, 2025). A primary or metastatic malignant neoplasm that affects the colon or rectum. "In vitro, assays also demonstrated higher PYGM expression in colorectal cancer cell lines (HT29, SW620, LOVO) compared to normal epithelial cells (NCM460)." (PMID 40873584, 2025).
depression (2 papers, 2022 to 2024). "In glycogenolysis, PYGM was downregulated in major depressive disorder and upregulated in ketosis, whereas PYGL was upregulated in both." (PMID 39125835, 2024). "Therefore, we proposed that GAA and PYGM might affect the occurrence and development of depression by regulating glycogen metabolism in the brain, while HK1 affects the survival and growth of neurons by regulating glycolysis, and eventually affects the mood of depressed patients." (PMID 35990602, 2022).
diabetes (2 papers, 2021 to 2025). "There were very few differences between the diabetes and control group in the untrained leg, where ACAT1 and PYGM were relatively more highly expressed in diabetes in type I and type IIX fibres, respectively." (PMID 40413649, 2025).
glioblastoma (2 papers, 2021 to 2022). The most malignant astrocytic tumor (WHO grade IV). "Also, the PYGM isoform was expressed in normal brain, while it was downregulated in glioblastoma patients." (PMID 35764612, 2022). "However, experimental data of bevacizumab treatment suggest that, unlike PYGL, neither PYGM or PYGB exhibited a detectable increase in U87 (glioblastoma) cells." (PMID 34177761, 2021).
Insulin resistance (2 papers, 2019 to 2023). Increased resistance towards insulin, that is, diminished effectiveness of insulin in reducing blood glucose levels. "Also, another study speculated that PYGM may be implicated in gastric cancer via the insulin resistance pathway." (PMID 31324732, 2019). "PYGM was reportedly involved in insulin and glycogen signaling pathways, insulin resistance and necroptosis." (PMID 37745699, 2023).
bladder cancer (1 paper, 2025). "However, we observed a high frequency of somatic mutations and copy number amplifications in the PYGM gene in bladder cancer patients." (PMID 38806990, 2025). "Previous studies have highlighted the involvement of PYGM, a glycogen phosphorylase isoform, in bladder cancer through its role in glycogen breakdown, essential for cancer cell survival and adaptation to low oxygen conditions." (PMID 38806990, 2025).
cardiomyopathy (1 paper, 2023). A disease of the heart muscle or myocardium proper. "PYGM: One patient (16/A) carried a pathogenic homozygous variant in PYGM (muscle isoform of glycogen phosphorylase, OMIM*608455); she showed cardiomyopathy, fatigue and cramps and inflammatory necrotizing features at muscle biopsy." (PMID 37510298, 2023).
Danon disease (1 paper, 2025). A lysosomal glycogen storage disease characterized by severe cardiomyopathy and variable degrees of muscle weakness, frequently associated with intellectual deficit. "Pompe disease linked to GAA (acid alpha-glucosidase) gene variations, Danon disease associated with LAMP2 (lysosomal associated membrane protein 2) gene variations, and McArdle disease caused by PYGM (muscle glycogen phosphorylase) gene variations all exhibit defective glycogen catabolism." (PMID 40868246, 2025).
head and neck cancer (1 paper, 2025). A primary or metastatic malignant neoplasm affecting the head and neck. "While PYGM is classically known for its role in glycogen metabolism in skeletal muscle, recent studies have implicated it in oncogenic metabolic pathways in gastric, renal, breast, and head and neck cancers." (PMID 40873584, 2025).
hereditary cardiomyopathy (1 paper, 2021). "These genes include VCP, COL6A2, SYNE2, PYGM gene, and TPM2, and they warrant investigation of the more complex interacting mechanism underlying the hereditary cardiomyopathy phenotypic features." (PMID 33567613, 2021).
hypertrophic cardiomyopathy (1 paper, 2021). A condition in which the myocardium is hypertrophied without an obvious cause. "In addition, the expression of muscle fiber genes (MYH, MYL, and TNNI) and glycogen metabolism-related genes (PKM, PFKM, and PYGM) decreased, indicating that the massive accumulation of TTX has an impact on the hypertrophic cardiomyopathy pathway and cardiac muscle contraction pathway." (PMID 34822510, 2021).
metastasis (1 paper, 2019). The spread or migration of cancer cells from one part of the body (where they first appeared) to another. "It was found that the down-regulation of PYGM and TNNC2 in HNSCC was positively associated with lymph node metastasis and advanced tumor stage, implying their potential role in HNSCC metastasis and progression." (PMID 31324732, 2019).
Myalgia (1 paper, 2023). "PYGM also played an important role in a variety of diseases such as early fatigue, myalgia, and contractures." (PMID 36941586, 2023).
non-small cell lung carcinoma (1 paper, 2021). A group of at least three distinct histological types of lung cancer, including non-small cell squamous cell carcinoma, adenocarcinoma, and large cell carcinoma. "Not only PYGM, but also PYGB level is up-regulated in different kinds of cancer such as colorectal cancer, hepatocellular carcinoma, prostate cancer, non-small cell lung cancer (NSCLC), and ovarian cancer." (PMID 33924466, 2021).
osteosarcoma (1 paper, 2025). A usually aggressive malignant bone-forming mesenchymal neoplasm, predominantly affecting adolescents and young adults. "Based on network pharmacology and transcriptomics, we identified ATP1A1, CLK1, SIGMAR1, PYGM, and HSP90B1 as the key targets of solasonine that influence the progression of osteosarcoma cells." (PMID 40831924, 2025). "In this study, five possible key targets of SS against osteosarcoma were finally identified: ATP1A1, CLK1, SIGMAR1, PYGM, and HSP90B1." (PMID 40831924, 2025). "It is speculated that ATP1A1, CLK1, SIGMAR1, PYGM, and HSP90B1 may serve as therapeutic targets for solasonine in the treatment of osteosarcoma." (PMID 40831924, 2025).
pituitary tumours (1 paper, 1999). "We investigated 23 sporadic pituitary tumours previously shown to harbour allelic deletion on 11q13 with the marker PYGM centromeric and within 50 kb of the MEN1 locus." (PMID 10389976, 1999).
rectal adenocarcinoma (1 paper, 2025). "Both MPGS and its central metabolic component, PYGM, were closely linked to M2 macrophage infiltration, immunosuppressive tumor microenvironments, and poor clinical outcomes in rectal adenocarcinoma." (PMID 40873584, 2025). "MPGS and PYGM may serve as novel biomarkers for risk stratification and guide personalized treatment strategies in patients with rectal adenocarcinoma." (PMID 40873584, 2025). "The signature comprises three macrophage-related genes—TIMP1, MAOB, and PYGM—that robustly stratify rectal adenocarcinoma (READ) patients by prognosis." (PMID 40873584, 2025).
rectal cancer (1 paper, 2025). A primary or metastatic malignant neoplasm that affects the rectum. "Our findings suggest that PYGM is a clinically relevant metabolic biomarker associated with immune modulation and survival outcomes in rectal cancer." (PMID 40873584, 2025). "Clinical tissue analyses and functional assays confirmed that PYGM is upregulated in rectal cancer and promotes tumor cell proliferation, migration, and M2 macrophage polarization." (PMID 40873584, 2025). "This study firstly highlights PYGM as a key metabolic and immunological regulator in rectal cancer, with significant prognostic and therapeutic implications." (PMID 40873584, 2025).
tauopathy (1 paper, 2026). Neurodegenerative disorders involving deposition of abnormal tau protein isoforms (tau proteins) in neurons and glial cells in the brain. "Astrocytic PYGM deficiency impaired mouse cognition, exacerbated tauopathy-related phenotypes in male PS19 mice, and disrupted astrocyte-neuron metabolic coupling." (PMID 41700129, 2026).
cancer (11 papers, 2019 to 2025). A tumor composed of atypical neoplastic, often pleomorphic cells that invade other tissues. "To further investigate the immune associations of the three hub genes (PYGM, MAOB, TIMP1), we performed immune cell infiltration analyses across 33 TCGA cancer types using ssGSEA and CIBERSORT algorithms." (PMID 40873584, 2025). "According to the Gene Expression Profiling Interactive Analysis (GEPIA) of the RNA sequencing data, PYGM expression is lower in many types of cancer than in normal tissues." (PMID 33924466, 2021). "The highly upregulated PYGM gene, an enzyme involved in glycogenolysis, is involved in diverse insulin and glucagon signaling, necroptosis, inflammatory response, cellular energy support, and cancer progression." (PMID 35741360, 2022). "PYGM was downregulated in GBM cancer compared to normal brain tissue." (PMID 35764612, 2022). "In summary, the RNA sequencing results from public databases as well as the experimental data from different research indicates that PYGM could be an important factor in cancer development and progression." (PMID 33924466, 2021). "It was demonstrated that compared with normal tissues, solid tumor had a higher glycogen content and the correct storage and management of glycogen may be relevant to cancer cell survival, implying the possible modulatory effect of PYGM in cancer." (PMID 31324732, 2019). "Previous study has demonstrated that flavopiridol could potently inhibit cell proliferation and induce apoptosis in HNSCC cells, suggesting that regulation of PYGM may serve as a promising anti-cancer strategy in HNSCC." (PMID 31324732, 2019). "Impressively, TK1, RRM2 and IMPDH1 were positively correlated with Myc/Myc signatures in multiple cancer types, whereas HSD17B6, PYGM and ACACB were negatively correlated with Myc/Myc signatures." (PMID 36629054, 2023). "Genes such as PYGM, BMF, MBNL3, DENND6A, REEP5, KLF6 and ITM2C are potentially regulated by circYPEL2 and involved in cancer-specific pathways, which are needed to be validated in further studies." (PMID 35052380, 2021). "Through data mining in a variety of databases, we illustrated that PYGM and TNNC2 were remarkably underexpressed in HNSCC, implying their possible role in cancer progression." (PMID 31324732, 2019). "MRNA levels of PYGM and TNNC2 were significantly down-regulated in a majority of cancer types and a multiple of independent analyses on HNSCC illustrated the down-regulation of PYGM and TNNC2 in tumor samples." (PMID 31324732, 2019). "The bioinformatics analysis of RNA sequencing data, confirmed experimentally, shows that both PYGM and TNNC2 could be potentially used as therapeutics or biomarkers for diagnosis and prognosis in this type of cancer." (PMID 33924466, 2021). "Since we have illuminated that the expression level of PYGM and TNNC2 was down-regulated in HNSCC samples, then we focused on whether mRNA expression of these genes was related to cancer grade or stage in individual patients." (PMID 31324732, 2019). "From our perspective, the overall underexpression of PYGM and TNNC2 in various cancers may imply the role of them in cancer development and progression and further investigation was of great value." (PMID 31324732, 2019).
tumor (9 papers, 2019 to 2025). "Further in vivo and mechanistic studies are warranted to clarify the causal relationships between PYGM expression and tumor progression in RC." (PMID 40873584, 2025). "Logistic regression analysis revealed that elevated PYGM expression was significantly associated with advanced T stage (p = 0.03), tumor anatomical subdivision (p = 0.003), and male sex (p = 0.009)." (PMID 40873584, 2025). "The expression of PYGM was elevated in tumor tissues and cell lines and significantly correlated with advanced tumor stages, anatomical location, sex and poor prognosis." (PMID 40873584, 2025). "Functional analyses, single-cell RNA sequencing, immunohistochemistry of clinical specimens, and in vitro cellular assays were employed to investigate the role of the MPGS hub gene, PYGM, in tumor biology and immune modulation." (PMID 40873584, 2025). "We furhter noted that there was a subset of tumours with high PYGM expression, although overall the tumour levels were lower than in normal brain." (PMID 35764612, 2022). "Moreover, a series of cellular assays confirmed that PYGM enhances tumor cell proliferation, inhibits apoptosis, and promotes migration and invasion." (PMID 40873584, 2025). "This suggests that PYGM may actively contribute to establishing an immunosuppressive tumor microenvironment by promoting M2 macrophage polarization, ultimately facilitating tumor progression." (PMID 40873584, 2025). "Subsequently, we further validated the relative lower mRNA levels of PYGM and TNNC2 in HNSCC tissues compared with adjacent normal tissues and demonstrated that the down-regulation of PYGM and TNNC2 was positively associated with lymph node metastasis and advanced tumor stage." (PMID 31324732, 2019). "Immunohistochemical analysis confirmed lower PYGM expression in the tumor area when compared to non-malignant tissue surrounding tumor cells." (PMID 33924466, 2021).
myopathy (7 papers, 2019 to 2025). A disease of the muscle in which the muscle fibers do not function properly. "· PYGM gene (11q13) mutations forms inactive enzymes which may induce myopathy. · Lipid Deposition Myopathy occurs when abnormal metabolism causes lipids to accumulate in skeletal muscle fibres, leading to lesions and degeneration." (PMID 37483534, 2022). "PYGM gene which encodes myophosphorylase enzyme was also related to HCM, as well as TPM2 gene, which was reported in patients with myopathy and DCM." (PMID 33567613, 2021). "Further genetic sequencing revealed missense VUS in the glycogen phosphorylase, muscle associated (PYGM) gene (c.580C>T) and tropomyosin 2 (TPM2) gene (c.536C>T), in addition to a missense pathogenic mutation in the valosin containing protein (VCP) gene, confirming the diagnosis of VCP myopathy." (PMID 33567613, 2021).
metabolic disorder (3 papers, 2010 to 2026). "McArdle disease (McA) is a rare metabolic disorder of autosomal recessive inheritance caused by pathogenic variants in the PYGM gene, which lead to a deficiency of the myophosphorylase enzyme." (PMID 41835783, 2026).
PYGM also shares sentences with these, for which no sentence is quoted: muscular dystrophy (4 papers); Hers disease (2); muscle disorders (2); Atrophy (1); brain tumour (1); Camptocormia (1); congenital myopathies (1); dermatomyositis (1); Forbes disease (1); fructose intolerance (1); gastric cancer (1); gingival cancer (1); glioma (1); glycogen storage disease type 13 (1); hepatocellular carcinoma (1); hypoaldosteronism (1); Krabbe disease (1); leukodystrophy (1); limb-girdle muscular dystrophy (1); metastatic tumors (1); Myotonia (1); neuronal ceroid lipofuscinosis (1); oral cancer (1); Retinopathy (1); tongue tumor (1); Wilson disease (1); α-thalassemia (1).